IDO1 (indoleamine 2,3-dioxygenase 1)
Diseases named in the same sentence as IDO1 in open-access papers (continued):
Sharing a sentence is not in itself a finding about the gene and the disease.
cancer (continued). "Parsing the enzymatic function of IDO1 in cancer aerobic glycolysis is crucial and has the potential to deepen our understanding of IDO1's role in cancer." (PMID 38706741, 2024). "Given the biological importance of IDO1 in cancer immune escape, several IDO1 inhibitors have advanced into clinical trials as monotherapies or in combination with conventional therapies for cancer treatment." (PMID 38755218, 2024). "ICD is of great interest in cancer immunotherapy, as it can enhance the effectiveness of immune checkpoint inhibitors, such as IDO1 inhibitors, by priming the immune system to recognize and attack cancer cells." (PMID 38591056, 2024). "The IDO1 pathway modulator Indoximod (d-1-MT), the IDO1 vaccination, and Epacadostat appears to be well tolerated by cancer patients." (PMID 38539263, 2024). "Next, co-expression analysis reveals that IDO1 was highly correlated with multiple immune-related gene expressions in pan-cancer." (PMID 38539263, 2024). "Prior studies have consistently shown that high IDO1 expression levels are correlated with favorable outcomes in breast and other cancers." (PMID 38780888, 2024). "It was demonstrated that PD-L1 expression is enhanced by IDO1 in cancer cells in an AhR-dependent manner and reduced by IDO1/TDO inhibition." (PMID 39337426, 2024). "High IDO1 expression often co-segregated with high expression of immune checkpoints across cancers and there was an independent, statistically significant, and linear relationship between IDO1 expression and that of PD-L1, STAT1, and CXCL10 transcripts." (PMID 38632994, 2024). "Other studies are also evaluating the combination of IDO1 and PD-1/PD-L1 inhibition for the treatment of cancer." (PMID 39054462, 2024). "The incidence of glycolysis in cancer cells is relatively high, but the effect of IDO1 on glycolysis in cancer cells is unclear." (PMID 38706741, 2024). "Previous studies reported higher expression of IDO1 in several human cancers, which correlates with poor prognosis." (PMID 39063133, 2024). "IFNγ secretion triggers the expression of indoleamine 2, 3-dioxygenase 1 (IDO1) in cancer cells, an enzyme that catabolizes Trp to generate metabolites that induce effector T cell dysfunction." (PMID 39154912, 2024). "Preclinical studies of IDO1 in experimental models of cancer using this strategy have shown promise." (PMID 38339226, 2024). "(S)-[18F]FETrp is a promising PET radiotracer for imaging IDO1 activity, one of the main enzymes involved in the tryptophan metabolism that plays a key role in several diseases including cancers." (PMID 38564046, 2024). "Both indoleamine 2,3-deoxygenase 1 (IDO1) and programmed death 1 (PD-1) mediated pathways suppress T-cell–mediated antitumor immunity, and IDO1 and the PD-1 ligand (PD-L1) are co-expressed in multiple cancer types and correlate with poor prognosis." (PMID 39054430, 2024). "Data mining analysis of IDO1 expression in cancer and para-cancer tissue using TCGA database showed a higher expression of IDO1 in cancer than in para-cancer tissue." (PMID 39239507, 2024). "Using an IDO1 inhibitor in conjunction with checkpoint inhibitors is considered a potential new approach in cancer treatment through immunotherapy." (PMID 39064305, 2024). "Historically, IDO1 positivity was mainly determined by immunohistochemistry (IHC), and the IDO1 expression in several types of cancer based on IHC varied across multiple studies." (PMID 38632994, 2024). "In the context of cancer, IDO1 is involved in suppressing effector T and NK cells and activating regulatory T (Treg) cells and myeloid-derived suppressor cells (MDSCs)." (PMID 39064305, 2024). "IDO1, indoleamine 2, 3-dioxygenase 1, is a widely expressed enzyme in human cancers that metabolizes tryptophan to kynurenine, which mainly interacts with effector T cells to impair their antitumor effects and facilitate immune escape." (PMID 38233752, 2024).
cancer (continued). "The emergence of IDO-1 inhibitors, including small molecules and monoclonal antibodies, has led to significant progress in cancer therapy, with several drugs advancing in clinical trials." (PMID 38342925, 2024). "A group of ICPs, including but not limited to PD-1/PD-L1, CTLA-4, lymphocyte activation 3 (LAG-3), TIM-3, VISTA, and indoleamine 2,3-dioxygenase 1 (IDO1), are shown to be dysregulated in cancer and infectious diseases." (PMID 38638433, 2024). "It’s interesting to note that the data showed that IDO1 is extensively co-expressed on cancer cells and stromal cells in various malignancies, particularly on dendritic cells (DC), Malignant cells, Macrophages, and Endothelial cells." (PMID 38539263, 2024). "Although most studies have established a direct relationship between elevated IDO1 levels and BC progression, some inconsistencies have been reported, raising questions on the role of IDO1 in cancer progression." (PMID 39371092, 2024). "In people, the IDO1 protein is not only expressed in some normal tissues and organs, but also in malignant tumors of different organ systems." (PMID 39061522, 2024). "In intestinal GC, CYP1B1 expression is inversely correlated with several cancer-related genes such as IDO1, a gene involved in the early steps of tryptophan metabolism that contributes to the endogenous AhR ligand kynurenine expression." (PMID 39200369, 2024). "The number of trials examining IDO1 inhibition in cancer therapy is still increasing since it has been established that targeting IDO1 is secure and well-tolerated." (PMID 38539263, 2024). "A recent study demonstrated that IDO1-triggered Trp depletion in cancer cells results in translation of Trp codons with Phe." (PMID 39154912, 2024). "In particular, Hypo-MS4 activity was positively associated with the expression levels of immune checkpoint genes, namely, CD274, PDCD1LG2, and IDO1, in multiple cancer types (P ≤ 0.01)." (PMID 38566132, 2024). "Our analysis indicated a positive correlation between B3GNT5 and immune activation markers, including CD276, PVR, NT5E, STING1, and TNF-SF18, as well as immunosuppressive genes TGF-ΒR1, IL-10PR, KDR, CD274, PDCD1LG2, IL-10, and IDO1 in the pan-cancer cohort." (PMID 39671359, 2024). "Across human cancer types, IL4I1 gene expression associates more strongly with a pan-tissue AhR activation signature compared to that of either IDO1 or TDO, indicating IL4I1-generated metabolites as key AhR activators in cancer." (PMID 39211039, 2024). "Given these preclinical and clinical data, IDO1 inhibitors/modulators have been developed and evaluated in clinical trials in patients with malignancies." (PMID 38632994, 2024). "FOXP3, found on regulatory T cells, and IDO1 (macrophages and dendritic cells) are higher in cancer than precancers or controls (p < 0.0001, p < 0.0001)." (PMID 39672307, 2024). "IDO1/TDO2 are aberrantly expressed in carcinomas and metabolize TRP into the immune-suppressive metabolite kynurenine (KYN), which can engage the aryl hydrocarbon receptor to drive immunosuppressive transcriptional programs." (PMID 38451784, 2024). "IDO1-positive carcinomas (n = 90): The histotypes were tubular (n = 59; 66%), cystic (n = 10; 11%), solid (n = 9; 10%), papillary (n = 5; 6%), tubular and solid (n = 3; 3%), tubulopapillary (n = 2; 2%), and tubular and cystic (n = 2; 2%)." (PMID 39061522, 2024). "Co-expression of IDO1 and programmed death-ligand 1 (PD-L1; the ligand of PD-1) has been observed in multiple cancer types." (PMID 37087488, 2023). "As IDO1 is one of enzymes that catalyze the first and rate-limiting step in the tryptophan-kynurenine signaling cascade, it is relevant to target IDO1 in cancer therapy." (PMID 36653774, 2023). "High levels of IDO1 expression by cancer cells can also drive MDSC expansion; Moreover, MDSCs also overexpress IDO1, triggering a positive feedback loop that reinforces and sustains the immune suppressive TME." (PMID 37114134, 2023).
cancer (continued). "Upon inhibition of IDO1 in cancer patients, the amount of Trp available as a substrate for IL4I1 would likely be replenished." (PMID 36765849, 2023). "The effects of IDO1 inhibition as a strategy to enhance anti-PD-1 therapy activity in cancer remained uncertain." (PMID 36798123, 2023). "Available reports demonstrate that epacadostat, as well as 1-L-MT, another IDO1 inhibitor, led to the activation of a caspase in cancer cells." (PMID 38201550, 2023). "Currently, selective IDO1/TDO2 inhibitors are being evaluated at different clinical phases to treat various cancers such as epacadostat, navoximod, BMS-986205, and PF-06840003." (PMID 37241719, 2023). "Given IDO1’s role in immune regulation and its potential as both a marker for rejection and an immunosuppressive factor, researchers have explored IDO1-targeted therapies for improving cancer outcomes." (PMID 38137602, 2023). "IDO1 helps cancer cells to escape the immune response by tryptophan depletion from the TME and by producing the catabolic products of tryptophan degradation that are toxic to T cells and NK cells." (PMID 37061716, 2023). "Cancer cells have evolved an innate program to respond to different cytokine stimuli (Ifnγ, IL-27, or IL-1) by upregulating both IDO1 and PD-L1 to promote cancer cell survival." (PMID 37985999, 2023). "IDO-1 protein is the next potential target for mediating immunosuppressive effects in cancer and expressed by numerous stromal cells, including fibroblasts." (PMID 38313431, 2023). "The boosted IDO1 activity has been proven to promote the development of an immunosuppressive microenvironment in cancer that inhibits antitumor immune responses." (PMID 37256178, 2023). "Indoleamine 2,3-dioxygenase 1 (IDO1) has been shown to promote cancer immune escape by catalyzing the breakdown of tryptophan to kynurenine." (PMID 37111620, 2023). "So far, therapeutic interference with the IDO1 pathway has yielded a wide range of responses in cancers of various lineages." (PMID 37061716, 2023). "Within the last decade, several tracers for assessing expression levels of IDO1 in cancers have been developed." (PMID 36674595, 2023). "Almost all cell types in tumors including the cancer cells can express IDO-1 that degrades tryptophan into kynurenine." (PMID 37180110, 2023). "For instance, miR-153 inhibits IDO1 expression in colon cancer cells, potentiating the anti-cancer activity of CAR-T cells aimed at the Epidermal Growth Factor receptor." (PMID 37296860, 2023). "For many years, IDO1 was viewed as one of the most promising targets for battling cancer through reactivation of the anticancer immune response." (PMID 36765849, 2023). "In the presented study, we validated that simultaneous targeting cancer cell along with downregulation of IDO1 expression results in strong antitumor effects in zebrafish xenografts." (PMID 38201550, 2023). "1-MT (NLG-8189) as well as other IDO1 inhibitors such as epacadostat, which has higher affinity for IDO1 than 1-MT, are being tested in multiple clinical trials for cancer." (PMID 36422996, 2023). "IDO1 is a significant rate-limiting enzyme that regulates the production of KP metabolites and is generally highly expressed in multiple human cancers." (PMID 37041200, 2023). "Indoleamine 2,3-dioxygenase 1 (IDO1) is a tryptophan metabolizing enzyme chronically activated in many cancer patients and its expression and activity correlate with a poor prognosis." (PMID 37122718, 2023). "The enzyme IDO1 has been reported to be a therapeutic target in cancers, with evidence from pharmacological and genetic studies." (PMID 38062922, 2023). "This property can be readily observed in single-cell RNA sequencing (scRNAseq) datasets and is a foundational concept behind the use of IDO1 inhibitors in cancer therapy." (PMID 37196768, 2023). "Fundamentally, kynurenine has an unmistakable role in cancer immune escape, making IDO1 a potential candidate to assist immunotherapy." (PMID 37456260, 2023).
cancer (continued). "Based on the literature, interstitial cells expressing IDO1 are likely macrophages or dendritic cells (DCs), which have been shown to upregulate IDO1 in various types of cancer, resulting in increased tumorigenesis." (PMID 36422996, 2023). "Potential targets for cancer therapy include efferocytosis-related genes and pathways, such as phosphatidylserine, TYRO3, MerTK, indoleamine-2,3-dioxygenase 1, membrane-linked protein V, CD 47, TGF-β, and IL-10." (PMID 37853449, 2023). "IDO-1 upregulation is suggested to be involved in cancer immune avoidance, making IDO inhibitors an attractive prospect for novel anti-cancer therapeutics when seeking to leverage the therapeutic benefits of immune system modulation." (PMID 37371332, 2023). "Because it plays an important role in the ability of cancer cells to evade attack by activated cytotoxic T-lymphocytes, IDO1 has been studied in many types of cancer." (PMID 36831659, 2023). "Together, these findings established a novel aspect of IDO1’s function in cancer, namely, its ability to contravene an anti-tumorigenic, IFNγ-mediated inflammatory environment that restricts new blood vessel formation in tumors." (PMID 37182174, 2023). "IDO1, with an important role in regulating the innate and adaptive immune response, is overexpressed in many types of cancers, including CRC." (PMID 38168324, 2023). "Tumors with high expression of IDO1 tend to increase metastatic invasion and have poor clinical outcomes in cancer patients." (PMID 37817770, 2023). "Combined suppression of efferocytosis and IDO1 dampened cancer cell death-induced immunosuppression and restricted mammary tumor progression in murine models." (PMID 38283351, 2023). "This indicates that normal cells can respond to cytokine stimuli to induce IDO1, but the IL-1β-mediated induction of IDO1 was specific to cancer cells." (PMID 37985999, 2023). "The expression of IDO1 has been shown to correlate with immune infiltration in multiple types of cancer." (PMID 37844995, 2023). "Epacadostat, a highly selective and orally available inhibitor of IDO1, is currently being studied in phase 3 clinical trials following positive results from multiple phase 1 and 2 studies for a variety of cancers." (PMID 37744363, 2023). "CD4, Fibronectin, CD27, CD11c, and IDO1 were the protein markers from ‘immune-rich cancer cell islets’ and ‘surrounding stromal leukocyte’ regions linked with a significant hazard ratio and overall survival." (PMID 37046826, 2023). "Strategies for Indolamine-2,3-dioxygenase 1 (IDO1) inhibition in cancer immunotherapy once produced encouraging results, but failed in clinical trials." (PMID 35963900, 2023). "In particular, the positive outcomes from animal studies have led to multiple clinical trials examining the potential of combining IDO1 inhibitor in combination treatments for cancer patients, including six clinical trials with BrCa patients." (PMID 37041200, 2023). "The best understood function of IDO1 is it's role as an immunoregulator in cancer, inhibiting the body's ability to fight diseased cells, but its role in autoimmune responses is less clear." (PMID 37275375, 2023). "High expression and over‐activation of indoleamine 2,3‐dioxygenase 1 (IDO1) are important reasons for the immune evasion of cancer cells." (PMID 36929586, 2023). "IDO1 has been demonstrated as expressing in 58% of human cancers, and its expression levels are correlated with the poor clinical outcome in several cancer types, such as melanoma, gynaecological cancers like endometrial carcinoma, liver and ovarian cancers." (PMID 36983678, 2023). "As a result, clinical studies employing IDO-inhibitors as well as an IDO1 peptide-based vaccine strategy for cancer treatment have been initiated." (PMID 37108483, 2023). "Indoleamine 2,3-dioxygenase 1 (IDO1) plays a key role in a variety of cancers, but its role and mechanism in EC are still unclear." (PMID 37903782, 2023).
cancer (continued). "We found that IDO1 expression overall was significantly higher in cancer patients of all stages than in HCs and also significantly higher in advanced stages than in lower stages of OSCC (ANOVA, p < 0.05)." (PMID 35963900, 2023). "Given the contradictory relationship between IDO1 expression and prognosis in different cancers, its biological functions in cancer have been extensively studied." (PMID 37903782, 2023). "Given the relationship between IDO1 expression and various types of human cancers, its biological functions and mechanism in EC were investigated." (PMID 37903782, 2023). "Macrophage expressing indoleamine 2,3-dioxygenase 1 (IDO1) increases to accelerate cancer progression." (PMID 37345086, 2023). "TRIM21 overexpression caused a significant increase in the ubiquitination of IDO1, whereas ubiquitination of IDO1 was noted to be reduced in TRIM21-depleted cancer cells." (PMID 37830596, 2023). "Subsequently, multiple phase 3 trials of various IDO1 inhibitors in combination with immune checkpoint inhibitors in other cancers were halted." (PMID 36900311, 2023). "The immunosuppressive role of IDO1 in protecting the hemiallogenic fetus was recognized even before its relevance to cancer was established." (PMID 37182174, 2023). "Recently, we and others discovered another mechanism by which tryptophan metabolism can promote cancer cell survival through IL4i1 and IDO1, namely, via suppression of ferroptosis." (PMID 37196768, 2023). "Given its biological importance, IDO1 has become an attractive target in cancer therapy, with initiated clinical trials investigating different IDO inhibitors." (PMID 37108483, 2023). "Indoleamine 2,3-dioxygenase 1 (IDO1) has attracted much attention in the field of cancer immunotherapy as an immunomodulatory enzyme." (PMID 37408559, 2023). "Inhibitors of IDO1 are widely applied in several clinical trials to overcome cancer immune escape and improve therapeutic potential." (PMID 37605514, 2023). "The metabolites of IDO-1 in cancers provide one-carbon units that annihilate effector T cells, and recruit immunosuppressive cells." (PMID 36517670, 2023). "As it is known that TDO2 regulates the Trp–Kyn–AhR pathway in a similar way to IDO1, this finding would support continued pursuit of this pathway as a therapeutic target in cancer." (PMID 37087488, 2023). "By contrast, of the 13 TDO2-overexpressing cancers, 6 co-express IDO1 (46%), 10 co-express FAMID (77%) and 9 (69%) co-express each of the two Trp transporters." (PMID 36286592, 2022). "When the bromopyrrole group of this compound is replaced by an indole moiety, (N-(3-((1H-Benzo[d]imidazol-1-yl) methyl) benzyl)-1H-indole-2-carboxamide) inhibits IDO1 in various cancer cell lines at low nanomolar levels and is more selective for IDO1." (PMID 36110557, 2022). "Consistent with the role of IDO1 in mediating tolerance to tumors, preclinical studies have shown that IDO1 inhibitors have a promising prospect in targeting several cancers." (PMID 36319978, 2022). "The T cell is controlled by indoleamine 2,3-dioxygenase (IDO1), which is important to immune tolerance; upregulated expression of IDO1 is reported in several types of cancer." (PMID 35909469, 2022). "Cancer cells are known to secrete cytokines, including interferons, which in an autocrine manner can regulate the constitutive IDO1 expression via the JAK1/STAT1 signaling pathway." (PMID 35997090, 2022). "IDO2 is expressed in fewer cancers, mainly those also expressing IDO1, though additionally in colon, non-small-cell, pancreatic and renal cancers." (PMID 36286592, 2022). "Activation of the kynurenine pathway enzyme indoleamine-2,3-dioxygenase (IDO1) modulates cellular activity in the brain, tolerogenesis in the immune system and is a major checkpoint in cancer development." (PMID 35371018, 2022). "Over the last several years, there has been a significant interest in targeting IDO1 for cancer therapy." (PMID 35997090, 2022).